AP2B1 (adaptor related protein complex 2 subunit beta 1)
Description:
Component of the adaptor protein complex 2 (AP-2). Adaptor protein complexes function in protein transport via transport vesicles in different membrane traffic pathways. Adaptor protein complexes are vesicle coat components and appear to be involved in cargo selection and vesicle formation. AP-2 is involved in clathrin-dependent endocytosis in which cargo proteins are incorporated into vesicles surrounded by clathrin (clathrin-coated vesicles, CCVs) which are destined for fusion with the early endosome. The clathrin lattice serves as a mechanical scaffold but is itself unable to bind directly to membrane components. Clathrin-associated adaptor protein (AP) complexes which can bind directly to both the clathrin lattice and to the lipid and protein components of membranes are considered to be the major clathrin adaptors contributing the CCV formation. AP-2 also serves as a cargo receptor to selectively sort the membrane proteins involved in receptor-mediated endocytosis. AP-2 seems to play a role in the recycling of synaptic vesicle membranes from the presynaptic surface. AP-2 recognizes Y-X-X-[FILMV] (Y-X-X-Phi) and [ED]-X-X-X-L- [LI] endocytosis signal motifs within the cytosolic tails of transmembrane cargo molecules. AP-2 may also play a role in maintaining normal post-endocytic trafficking through the ARF6-regulated, non-clathrin pathway. During long-term potentiation in hippocampal neurons, AP-2 is responsible for the endocytosis of ADAM10. The AP-2 beta subunit acts via its C-terminal appendage domain as a scaffolding platform for endocytic accessory proteins; at least some clathrin-associated sorting proteins (CLASPs) are recognized by their [DE]-X(1,2)-F-X-X-[FL]-X-X-X-R motif. The AP-2 beta subunit binds to clathrin heavy chain, promoting clathrin lattice assembly; clathrin displaces at least some CLASPs from AP2B1 which probably then can be positioned for further coat assembly.
Synonyms: ADTB2; CLAPB1; AP105B; AP2-BETA
Tractability: Small molecule: a structure with a bound ligand is known; it has a binding pocket of medium quality. Antibody: UniProt places it where antibodies can reach, with high confidence; its Gene Ontology location is reachable by antibodies, with high confidence. PROTAC: ubiquitination databases record sites on it; its protein half-life has been measured.
Gene: Protein-coding gene on chromosome 17 (35,578,046 to 35,726,417, forward strand). Ensembl gene ENSG00000006125.
Subcellular location: Cell membrane; Membrane, coated pit
Subcellular location (Human Protein Atlas): Vesicles
Pathways (Reactome):
Disease: Dengue Virus Attachment and Entry; Nef Mediated CD4 Down-regulation; Nef Mediated CD8 Down-regulation; Potential therapeutics for SARS
Signal Transduction: Retrograde neurotrophin signalling; WNT5A-dependent internalization of FZD2, FZD5 and ROR2; WNT5A-dependent internalization of FZD4
Developmental Biology: EPH-ephrin mediated repulsion of cells; Recycling pathway of L1
Transport of small molecules: LDL clearance; VLDLR internalisation and degradation
Vesicle-mediated transport: Cargo recognition for clathrin-mediated endocytosis; Clathrin-mediated endocytosis
Immune System: MHC class II antigen presentation
Neuronal System: Trafficking of GluR2-containing AMPA receptors
Gene Ontology:
Molecular function: clathrin adaptor activity; clathrin binding; protein binding; signal sequence binding; protein-containing complex binding
Biological process: clathrin-dependent endocytosis; synaptic vesicle endocytosis; postsynaptic neurotransmitter receptor internalization; vesicle-mediated transport; chemical synaptic transmission; clathrin coat assembly; intracellular protein transport; neurotransmitter secretion; positive regulation of endocytosis; positive regulation of protein localization to membrane; protein transport
Cellular component: AP-2 adaptor complex; clathrin adaptor complex; membrane; plasma membrane; AP-1 adaptor complex; clathrin-coated endocytic vesicle; clathrin-coated endocytic vesicle membrane; cytoplasmic side of plasma membrane; cytosol; endocytic vesicle membrane; endolysosome membrane; clathrin coat; cytoplasmic vesicle; endomembrane system; extrinsic component of presynaptic endocytic zone membrane; glutamatergic synapse; lysosomal membrane; membrane coat; postsynaptic endocytic zone; synapse; synaptic vesicle
Genetic constraint (gnomAD): Loss-of-function variants: 16 observed, 88.27 expected, observed/expected ratio (o/e) 0.18, 90% interval 0.12 to 0.28. The upper end of that interval is the gene's LOEUF score, 0.28, which puts it in group 1 of 6, group 1 being the genes least tolerant of losing a copy. Missense variants: 512 observed, 1,114.5 expected, observed/expected ratio (o/e) 0.46, 90% interval 0.43 to 0.49. Synonymous variants: 359 observed, 409.28 expected, observed/expected ratio (o/e) 0.88, 90% interval 0.8 to 0.96.
Homologues: Orthologues: chimpanzee AP2B1 (100% identical), dog AP2B1 (100% identical), rat Ap2b1 (100% identical), mouse Ap2b1 (99% identical), pig AP2B1 (99% identical), rabbit AP2B1 (99% identical), macaque AP2B1 (99% identical), tropical clawed frog ap2b1 (95% identical), zebrafish ap2b1 (95% identical), Drosophila melanogaster rb (26% identical), Caenorhabditis elegans apb-3 (22% identical). Paralogues in human: AP1B1 (83% identical), AP3B2 (26% identical), AP3B1 (26% identical), AP4B1 (22% identical).
Diseases named in the same sentence as AP2B1 in open-access papers:
AP2B1 is named in the same sentence as 28 diseases in open-access papers, as found by Europe PMC text mining. Sharing a sentence is not in itself a finding about the gene and the disease. The quoted sentences say what the papers report.
Alzheimer disease (6 papers, 2014 to 2024). A progressive, neurodegenerative disease characterized by loss of function and death of nerve cells in several areas of the brain leading to loss of cognitive function such as memory and language. "Increased levels of AP2B1 have been recently observed in the cerebrospinal fluid of Alzheimer’s disease patients." (PMID 36702823, 2023). "Although most of the genes were involved in several of these pathways, some of them were restricted to Huntington’s disease (AP2B1, CREB3L4, POLR2H and SOD1), to Alzheimer ́s disease (NAE1, FAS) or to Parkinson’s disease (PARK7)." (PMID 24742402, 2014).
breast carcinoma (1 paper, 2022). "The data suggested that the four genes, AP2B1, APP, GPNMB and DLST, were highly expressed in breast cancer and that AP2B1 was a suitable prognostic marker for breast cancer." (PMID 35678671, 2022). "In addition, the HPA database demonstrated that AP2B1, APP, GPNMB and DLST were highly expressed in breast cancer; the increased expression of AP2B1 (cut-off value, 75%) was significantly associated with the survival rate (p = 0.044) of 1075 patients with breast cancer." (PMID 35678671, 2022). "The human protein atlas database also found that AP2B1, APP, GPNMB and DLST were highly expressed in breast cancer and that AP2B1 (cut-off value, 75%) was significantly associated with survival rate (p = 0.044)." (PMID 35678671, 2022). "The present study identified four genes (AP2B1, APP, GPNMB and DLST) that were significantly downregulated by luteolin in breast cancer cell lines." (PMID 35678671, 2022).
cerebellar degeneration (1 paper, 2025). Degeneration of the cerebellum. "AP2B1 is a protein coding gene implicated in cerebellar degeneration and plays a crucial role in synaptic neurotransmission." (PMID 40799755, 2025).
cleft palate (1 paper, 2012). Cleft palate is a fissure type embryopathy that affects the soft and hard palate to varying degrees. "Ablation of Ap2b1, which encodes another of the AP2 subunits, causes cleft palate in mouse." (PMID 22371254, 2012).
fragile X syndrome (1 paper, 2025). A genetic syndrome caused by mutations in the FMR1 gene which is responsible for the expression of the fragile X mental retardation 1 protein. "AP2B1 upregulation disrupts synaptic plasticity, leading to neuronal and cognitive dysfunctions observed in Fragile X syndrome." (PMID 40790242, 2025).
kidney cancer (1 paper, 2015). Primary or metastatic malignant neoplasm involving the kidney. "Thus, the changes we identified in alternative splicing of these genes are appealing potential diagnostic markers for tumor initiation in several cancers, and FBLN2, AP2B1 and TCF20 are also good prognostic markers for patient survival in breast, lung, and kidney cancers, respectively." (PMID 25908786, 2015).
lung adenocarcinoma (1 paper, 2021). A carcinoma that arises from the lung and is characterized by the presence of malignant glandular epithelial cells. "The heatmap reveals that HNRNPLL|53258|AT, CA5B|98313|ES, MEGF6|315|ES, and CDKN2A|86000|AP may have positive effects on lung adenocarcinoma while BEST3|23330|AT, TTC39C|44852|AP, AP2B1|40327|AD, LETM2|83399|AT, and MKL1|62348|AP can have adverse effects." (PMID 35004299, 2021).
lung carcinoma (1 paper, 2020). "Many new targets of IgGs in lung cancer were non-cell surface proteins, but we noticed that many targets of these IgGs were adaptor proteins, such as the AP-2 complex including AP2A1, AP2A2, AP2B1, AP2S1, and AP2M1." (PMID 32580738, 2020).
non-small cell lung carcinoma (1 paper, 2022). A group of at least three distinct histological types of lung cancer, including non-small cell squamous cell carcinoma, adenocarcinoma, and large cell carcinoma. "The resistance phenotype to cancer drugs is associated with an increase in the protein level of AP2B1 in non-small cell lung cancer." (PMID 35678671, 2022).
otitis media (1 paper, 2009). Inflammation of the anatomical structures of the middle ear, which is most often caused by an infectious process. "The very tip of our 17q12 linkage peak occurs in AP2B1 (adaptor-related protein complex 2, beta 1 subunit), which plays a role in Nef-mediated CD8 down-regulation, and children with recurrent otitis media had low numbers of CD8+-producing IFN g cells in adenoids." (PMID 19728873, 2009).
papillary thyroid cancer (1 paper, 2024). "Of significance, AP2A1, AP2B1 and AP2M1 were highly expressed in papillary thyroid cancer (PTC) with the more aggressive BRAF-like gene signature compared to RAS-like PTC, as well as in the independent PTC dataset GSE60542." (PMID 37921808, 2024).
tauopathies (1 paper, 2024). "Our results regarding AP2B1 and APP suggest that the early stages of the lysosomal pathway are specifically altered in the FTLD-linked disorders (and potentially particularly the primary tauopathies) when compared to those disorders with underlying AD pathology." (PMID 37917233, 2024).
cancer (9 papers, 2015 to 2025). A tumor composed of atypical neoplastic, often pleomorphic cells that invade other tissues. "AP2B1, a member of the AP2 family, acts as either an oncogene or tumor suppressor in various human cancers." (PMID 31296583, 2019). "A statistically significant correlation was observed for AP2B1, TCF20 and FBLN2 in one or two of the cancer types examined." (PMID 25908786, 2015). "Some of the common cancer-regulated alternative splicing events we identified in genes such as FN1, FBLN2, AP2B1 and TCF20 are most likely oncogenic drivers." (PMID 25908786, 2015). "Taken together, it is likely that splicing changes in FN1, FBLN2, AP2B1 and TCF20 are also drivers of cancer initiation and progression, which still needs to be determined functionally." (PMID 25908786, 2015).
tumor (5 papers, 2015 to 2024). "Other genes such as RBBP4, DNA2, AP2B1, etc. may also affect tumor immune responses through their respective molecular functions." (PMID 39083127, 2024).
AP2B1 also shares sentences with these, for which no sentence is quoted: depression (2 papers); cervical carcinoma (1); eosinophilic gastroenteritis (1); Huntington disease (1); infection (1); malaria (1); neuroblastoma (1); parasite infections (1); Parkinson disease (1); pulmonary disease (1); sarcoidosis (1); Stroke (1); testicular cancer (1); viral infection (1).